RRM2 (ribonucleotide reductase regulatory subunit M2)
Diseases named in the same sentence as RRM2 in open-access papers (continued):
Sharing a sentence is not in itself a finding about the gene and the disease.
tumor (continued). "RRM2 exhibited elevated expression in tumor tissue, which was amplified with an increased malignancy of the HCC subtype." (PMID 38785515, 2024). "RRM2 was reported to mainly locate in the cytoplasm and occasionally in the nucleus, which was also noticed in iCCA tumor tissues." (PMID 39243109, 2024). "This is consistent with findings discussed earlier that elevated expression of RRM2 can overcome the tumour suppressive barrier of OIS." (PMID 39206868, 2024). "In our study, we employed PCR, WB, and IHC techniques to validate the increased levels of RRM2 in tumor specimens obtained from our clinical cohort." (PMID 40625451, 2024). "RRM2 expression levels in BRCA, KIRC, LUAD, LUSC, STAD, THCA, and THYM were negatively correlated with the infiltration level of tumor-associated endothelial cells but were positively correlated with KIRP and LGG." (PMID 38635758, 2024). "In the remaining viable tumor cells within these two tumors, we found much lower levels of RRM2 but higher levels of RRM2B compared to PT1 (vii & xi vs. iii, viii & xi vs. iv)." (PMID 36882565, 2023). "In recent years, RRM2 has been defined as a vital component in tumor progression, as well as a promising tumor biomarker for many cancers." (PMID 37056349, 2023). "Meanwhile, the expression levels of RRM2 in tumor and paraneoplastic tissues were further verified by qRT-PCR and Western Blotting." (PMID 37056349, 2023). "Adding a low-dose of RRM2 inhibitor MK1775 to irinotecan was able to delay tumor relapse in an HB PDX model compared to irinotecan treatment alone." (PMID 36882565, 2023). "With the knockdown of the expression level of RRM2, the activity of ribonucleotide reductase, the growth of cancer cells, and tumor metastasis were downregulated." (PMID 37137710, 2023). "A reversed RRM2B-to-RRM2 switching was evident in the relapsed tumor 34 days post treatment with the regaining of RRM2 punctate signals and its association with Ki67 positivity when RRM2B dropped." (PMID 36882565, 2023). "The increased level of RRM2 expression were positively correlated with a higher grade of T stage (P <0.05), Pathologic stage (P <0.05), tumor status (P <0.01), histologic grade (P <0.001), and AFP levels (P <0.001)." (PMID 37056349, 2023). "RRM2 has been implicated in epithelial to mesenchymal transition (EMT) and tumor-associated angiogenesis." (PMID 36597126, 2023). "In the univariate analysis, the expression of RRM2, T stage, M stage, pathologic stage, and tumor status were negatively correlated with OS (P <0.05)." (PMID 37056349, 2023). "The results demonstrated that SNHG4 KD notably inhibited xenograft tumor growth in volume and weight, whereas RRM2 restoration partially recovered the growth of xenograft tumors." (PMID 37596700, 2023). "A recent study found that gene expression of RRM2 was associated with the metabolism of 5-FU and platinum, and the gene overexpression of RRM2 was shown particular in tumor tissues." (PMID 37033615, 2023). "Further analysis using multivariate Cox regression showed that tumor status (P<0.01) and RRM2 expression (P<0.05) were independent prognostic factors of OS in HCC." (PMID 37056349, 2023). "In animal models, combined treatment of HZ-A-018 and 5-FU also suppressed the expression of RRM2, as determined by Western blotting of tumor tissues and in situ immunohistochemistry of tumor sections." (PMID 37033615, 2023). "In the univariate analysis, the T stage, M stage, pathologic stage, tumor status, and RRM2 expression level affected the prognosis of HCC patients (P <0.05)." (PMID 37056349, 2023). "Combining an RRM2 inhibitor with chemotherapy showed an effective delaying of HB tumor relapse in vivo." (PMID 36882565, 2023). "Angiogenesis is a major element in the recurrence and spread of cancer, and ribonucleotide reductase regulatory subunit M2 (RRM2) has been provided to play a key control effect in restricting the growth of tumor capillaries." (PMID 38169723, 2023).
tumor (continued). "The authors proposed that miR-20a-5p potentially regulates the expression of the RRM2 protein, thereby exerting an influence on the sensitivity of tumour cells to GEM." (PMID 37803304, 2023). "In recent studies, RRM2 was reported to control tumor progression and drug resistance, and was able to regulate the sensitivity of renal cancer cells to Sunitinib and PD-1 Blockade via modulating AKT pathway." (PMID 37033615, 2023). "This pan-cancer study aimed to evaluate the effect of high expression of RRM2 the tumor prognosis based on clinical information collected from The Cancer Genome Atlas (TCGA) and The Genotype-Tissue Expression (GTEx) databases." (PMID 36202136, 2022). "Altogether, the upregulation of RRM2 mediated by ncRNAs correlates with poor prognosis and tumor immune infiltration of HCC." (PMID 35911380, 2022). "In line with our findings, it was reported that RRM2 facilitates tumor immune infiltration by inhibiting ferroptosis in LUAD." (PMID 35740608, 2022). "BNIP3 and GOT1 were downregulated gradually with the increase in the grade, but RRM2 increased gradually with the increase in the grade and stage, which revealed that three target genes were closely related with tumor progression." (PMID 35350243, 2022). "EGLN1, MIF, PANX1, and RRM2 showed a consistently high expression in 15 tumor samples compared to paired normal tissues." (PMID 35311093, 2022). "In conclusion, our findings suggest that the upregulation of RRM2 mediated by ncRNAs correlates with poor prognosis and tumor immune infiltration of HCC patients." (PMID 35911380, 2022). "OMT-induced circ_0008460 downregulation, miR-197-3p upregulation, and RRM2 protein inhibition were all recovered by lenti-circ_0008460 in tumor tissues." (PMID 35609310, 2022). "To determine the biological functions of RRM2, we divided the tumor samples into high and low expression groups." (PMID 36202136, 2022). "These outcomes depict that RRM2 possibly has a major impact on the tumor immune microenvironment (TIME)." (PMID 35740608, 2022). "In vivo assay further manifested that OMT reduced tumor growth by resulting in downregulation of circ_0008460 to regulate miR-197-3p and RRM2 levels." (PMID 35609310, 2022). "In concurrence with the results of bioinformatic prediction, the RRM2 mRNA level was also elevated in BLCA tumor tissues by qRT-PCR." (PMID 35740608, 2022). "The inhibition of RRM2 decreased the expression of PD-L1, and the tumor regression effect was better when both RRM2 and PD-1 were inhibited." (PMID 36612193, 2022). "It was observed that RRM2 expression mainly correlated with immune checkpoint genes in tumor tissues of HNSC, KICH, KIRC, LIHC, PRAD, THCA, and UVM." (PMID 36202136, 2022). "In accordance with these studies, we found that RRM2 expression in tumor tissues was increased compared to that in normal tissues across pan-cancer." (PMID 35740608, 2022). "In these immunostimulatory marker genes, CD276, MICB, NT5E, PVR and ULBP1 had a significantly positive correlation with RRM2 expression in most tumor types." (PMID 35740608, 2022). "Meanwhile, using TCGA and the Tumor Immune Estimation Resource 2 (TIMER 2), the associations between RRM2 expression, immune infiltration, and immune-related genes were assessed." (PMID 36518297, 2022). "The expression of RRM2 between normal tissues and tumor tissues was also validated in the GEPIA database." (PMID 35360870, 2022). "For instance, the AFAP1-AS1/miR-139-5p axis controls tumor growth and attenuates chemotherapy resistance by targeting RRM2." (PMID 36678539, 2022). "Herein, circ_0008460 was elucidated to regulate the anti-tumor function of OMT in CC progression by targeting miR-197-3p/RRM2 axis." (PMID 35609310, 2022). "The overexpression of RRM2 significantly enhances the invasiveness of the cells and plays a key role in determining the degree of tumor malignancy." (PMID 36247089, 2022).
tumor (continued). "The expression levels of BNIP3 and GOT1 decreased gradually with the increase in grades, but RRM2 increased gradually with the increase in clinical grades and stages, which revealed that three target genes were closely related to tumor progression." (PMID 35350243, 2022). "Infiltration of tumor-associated macrophages (TAMs) was significantly correlated with RRM2 expression in the majority of tumor types." (PMID 36518297, 2022). "We analyzed the difference in mRNA and protein expression, pathological stage, survival, mutation, tumor microenvironment (TME), and immune cell infiltration in relation to RRM2." (PMID 36518297, 2022). "This study provided a new perspective for understanding RRM2 in cancers and new strategies for tumor immunotherapy." (PMID 35740608, 2022). "Collectively, our findings elucidated that high expression of RRM2 correlates with prognosis and tumor immunotherapy in pan-cancer." (PMID 36202136, 2022). "We hope to provide a new perspective for understanding RRM2 in cancers and new strategies for tumor immunotherapy." (PMID 35740608, 2022). "Despite these trends, further investigation is required to elucidate the additional roles of RRM2 in tumor progression and development, specifically its molecular contributions to tumor immunomodulation." (PMID 36518297, 2022). "In parallel, miR-20a-5p, another member of miR-20, acts as a tumor suppressor of NSCLC by regulating the ribonucleotide reductase regulatory subunit M2 (RRM2)-mediated PI3K (phosphatidylinositol 3-kinase)/Akt (serine/threonine kinase 1) axis." (PMID 34968160, 2022). "We verified the upregulated protein expression of RRM2 in tumor tissue (n = 154) compared to adjacent normal tissue by IHC staining." (PMID 36518297, 2022). "The profiles illustrate that RRM2 is putatively involved in tumor immune infiltration and functions critically in the immune-oncological interactions." (PMID 35740608, 2022). "piR-39980, which has been reported to have an oncogenic function in human osteosarcoma cells, has been found to have strong anti-tumor activity in fibrosarcoma (early metastatic lethal tumor) by repressing RRM2." (PMID 35755302, 2022). "In the univariate Cox regression analysis, RRM2, the number of positive lymph nodes, ER, PR, Her-2, Grade, Tumor size, Tumor stage have significant correlations with OS (P<0.001)." (PMID 35290409, 2022). "We performed a pan-cancer analysis of the potential correlation between RRM2 gene expression and stromal score, immune score, tumor-infiltrating immune cells, and immune factors." (PMID 36202136, 2022). "Since accumulating evidence indicates that RRM2 regulates tumor immunity, we also paid attention to immune pathways." (PMID 36202136, 2022). "In precision medicine for tumors, targeting of RRM2 has emerged as a therapeutic method for some cancers as it inhibits proliferative cell cycle and regulates autophagy pathways to suppress tumor progress." (PMID 35651787, 2022). "Univariate and multivariate Cox regression analyses of TCGA-BRCA data revealed that RRM2 expression was significantly correlated with age, tumor stage, N, and M stage." (PMID 36678539, 2022). "IHC and Western blot results indicated that RRM2 expression decreased in MDA-MB-231 tumor xenograft models treated with BBR." (PMID 36678539, 2022). "As shown in the Gene Expression Profiling Interactive Analysis database, RRM2 is frequently overexpressed in multiple tumor tissues, including liver cancer." (PMID 35609318, 2022). "In this study, RRM2 expression data were generated for patients belonging to diverse age groups and tumor stages." (PMID 36202136, 2022). "Moderate and high RRM2 expression were common in cases with large tumour size and high lymph node stage, in agreement with other studies." (PMID 34986845, 2022). "We also investigated the functions of RRM1 or RRM2 in vivo and found that tumor growth was inhibited following knockdown of RRM1 and RRM2, compared with the control group." (PMID 35546402, 2022).
tumor (continued). "Taken together, OMT resulted in tumor growth repression by targeting circ_0008460/miR-197-3p/RRM2 axis in vivo." (PMID 35609310, 2022). "The novel RRM2 inhibitor osalmid had anti-tumor activity, including inhibiting proliferation and migration, promoting cell apoptosis, blocking cell cycle, and inducing DNA damage of HCC cells." (PMID 35928445, 2022). "In this study, we investigate how RRM2 mediates the anti-tumor effect of PECT on GBM via reducing CDK1 protein expression and examined the functional significance of autophagy and cell cycle in GBM treatment." (PMID 35651787, 2022). "The results showed that the expression of RRM2 in tumor tissues was higher than that in normal lung tissues." (PMID 36153508, 2022). "Further results showed that miR-4500 reduced the tumor growth rate and the tumor volume in tumor xenograft-induced nude mice via RRM2 downregulation." (PMID 35499045, 2022). "In vivo, our results showed that PECT suppressed tumor proliferation, accompanied by reducing tumor weight and tumor weight/mouse weight, and downregulating RRM2 mRNA and protein expression compared to that in controls." (PMID 35651787, 2022). "Higher RRM2 expression in our patient cohort was furthermore correlated with larger tumor size (p = 0.019)." (PMID 34439352, 2021). "RRM2 has been reported to be an independent predictor of early recurrence of HCC, suggesting that RRM2 potentially promotes tumor cell metastasis." (PMID 33380233, 2021). "Based on these, the protein and mRNA levels of RRM2 were found to be upregulated (high expression groups) in 51 (75%) and 62 (35.03%) tumor cases of our cohort and TCGA cohort, respectively." (PMID 33670609, 2021). "In a study that reported RRM2 acetylation at K95 suppresses tumor cell growth in vitro and in vivo, and is therefore a potentially attractive strategy for cancer therapy." (PMID 34675265, 2021). "Celastrol can suppress progression of PC cells via down-regulating RRM2 expression, showing tumor-promoting function of this pathway." (PMID 34943856, 2021). "Recent studies have shown that RRM2 facilitated tumor immune infiltration through inhibiting ferroptotic death in LUAD patients." (PMID 35096011, 2021). "In case of tumor spheroids, RRM2 and VEGF were both significantly downregulated by PF6- and NF70-mediated siRNA delivery, whereas lipofection was only significantly effective in knocking down VEGF." (PMID 34683911, 2021). "Cutoff values of 2.5 and 11.09 were used for tumor classification and patient dichotomizing into two groups according to RRM2 protein and mRNA levels, respectively." (PMID 33670609, 2021). "A large amount of evidence shows that RRM2 functions as an oncogenic factor to promote the progression of various tumors, regulate tumor cell differentiation and metastasis, and modulate chemotherapy resistance." (PMID 34895038, 2021). "RRM2 labeling was membranous–cytoplasmic in the vast majority of cancer cells, whereas it was mainly restricted to the cytoplasm of non-tumor cells." (PMID 33670609, 2021). "The expression levels of ALOX12B, GPX2, DDIT4, GDF15, and RRM2 in tumor tissues were significantly higher than those in the normal lung tissues." (PMID 34307361, 2021). "CALAA-01 is a siRNA-based therapeutic interfering RRM2 that is able to recognize tumor cells expressing transferrin receptors." (PMID 34863235, 2021). "The most frequently mutated genes in the tumor fragments of women were USH2A, ATM, and IGF2R; in female dogs, they were USH2A, BRCA2, and RRM2." (PMID 34680380, 2021). "Our results also demonstrated that RRM2 silencing collaborated with radiotherapy to promote cell apoptosis and inhibit tumor growth." (PMID 33858512, 2021). "In accordance with a suggested impact of RRM2 expression levels on tumor cell viability, specific siRNA-mediated RRM2 silencing indeed led to an accompanying significant decrease in cell count in both models (p < 0.001)." (PMID 34439352, 2021).
tumor (continued). "Among them, the difference of RRM2 was the most significant, the expression level of RRM2 in tumor tissues was significantly higher than that in normal tissues." (PMID 34324544, 2021). "RRM2 plays an active role in tumor development and progression, and high RRM2 expression is associated with poorer patients outcomes in cancers." (PMID 34234118, 2021). "The tumour suppressor RRM2 was slightly upregulated in 48 h treatment whereas Rac1, a protein contributing to invasion, was less abundant in NBL cells treated with MEVs for 72 h." (PMID 33805332, 2021). "Our results demonstrated that RRM2 silencing had anti-tumor values and activated the cGAS/STING signaling pathway." (PMID 33858512, 2021). "In the TCGA-LUAD cohort, we compared the mRNA expression of RRM2 in tumor and normal or their adjacent tissues." (PMID 33123291, 2020). "To this end, we used mice containing the Chk1 and/or Rrm2 transgenes, and assessed tumor-free survival of these mice." (PMID 32253367, 2020). "Univariate Cox analyses in overall survival showed that tumor stage, TNM classification, and RRM2 were acting potential risk roles in LUAD." (PMID 33123291, 2020). "Next, we further identified 21 anti-tumor drugs (e.g., Cladribine, Gallium nitrate, Dinaciclib, Alvocidib, Suramin) targeting RRM2, CDK1 and CCNA2." (PMID 33083112, 2020). "Lastly, the correlations between immune signatures of immunomodulators, chemokines, and 28 tumor-infiltrating lymphocytes (TILs) and RRM2 were examined by tumor purity-corrected partial Spearman's rank correlation coefficient through TIMER portal." (PMID 33123291, 2020). "Correlate analysis provides an exhaustive characterization of the association between RRM2 and immune signatures in LUAD patients, indicating that RRM2 is a crucial player in immune escape in the tumor microenvironment." (PMID 33123291, 2020). "RRM2 is also considered a vital component in tumor progression, a regulator of some oncogenes and a promising tumor biomarker for many cancers." (PMID 33372599, 2020). "MGI is a gene expression assay, measuring the expression of five genes (BUB1B, CENPA, NEK2, RACGAP1, RRM2) related to histological grade and tumor progression, which recapitulates tumor grade and can predict the clinical outcome with high performance." (PMID 33287297, 2020). "The present study found that RRM2 was highly expressed in LUAD tumor tissue and significantly predicts a poor prognosis; also, the higher tumor stage got a higher expression." (PMID 33123291, 2020). "In our story, the investigation of differential expression in LUAD found that RRM2 was highly expressed in tumor tissues, which was subsequently examined in multiple independent cohorts." (PMID 33123291, 2020). "Silencing of RRM2 using RRM2 shRNA significantly inhibited growth of xenografted tumors (panel 1 vs. panel 2), suggesting that RRM2 is essential for tumor growth." (PMID 31324785, 2019). "In conclusion, our study suggests that in a mouse subcutaneous transplanted tumor model, expression of RRM2 mRNA and protein and the volume of subcutaneous transplanted tumors were the lowest in tumors of mice treated with siRNA + cisplatin." (PMID 31673243, 2019). "RRM2 is a key enzyme in DNA synthesis and repair pathways, and high expression of RRM2 is relative to tumor angiogenesis, invasion and metastasis." (PMID 31422942, 2019). "The expression of RRM1 and RRM2 genes in tumor tissues were both significantly increased in all TNM stages of LUSC and LUAD, compared with their corresponding adjacent normal lung tissue samples." (PMID 31637211, 2019). "In support of Sirt2’s tumor-promoting function, here we discovered that Sirt2 deacetylates RRM2 to enhance RNR activity leading to increased dNTPs pool size and proliferation of cancer cells." (PMID 31324785, 2019). "In contrast, downregulation or silencing of the expression of RRM2 can lead to apoptosis of malignant tumor cells, thereby inhibiting cell proliferation, metastasis, and reversing cell resistance." (PMID 31673243, 2019).